EGFR (epidermal growth factor receptor)
Diseases named in the same sentence as EGFR in open-access papers (continued):
Sharing a sentence is not in itself a finding about the gene and the disease.
lung adenocarcinoma (continued). "We examined the expression of miR-26a in 5 non-small cell lung cancer (NSCLC) tissue samples, which were all EGFR-TKI resistant lung adenocarcinoma." (PMID 27285768, 2016). "In conclusion, in this retrospective study, we have demonstrated that BM was more common among patients with EGFR-mutant lung adenocarcinoma (vs. wild-type EGFR lung adenocarcinoma)." (PMID 27486770, 2016). "The results of this study are potentially relevant not only to EGFR-driven lung adenocarcinoma, but also to other cancers where glycolysis is driven by dominantly-acting oncogenes." (PMID 27861144, 2016). "The main objective of the present study was to analyze the EGFR, KRAS and ALK mutation status in a representative cohort of patients in Croatia with lung adenocarcinomas and to correlate the mutational status with clinical data." (PMID 27655296, 2016). "For example, EGFR and KRAS are two of the most commonly mutated genes in lung adenocarcinomas; however they are rarely mutated in lung squamous cell carcinomas." (PMID 26603430, 2015). "Our finding that the PTP-defective Shp2CSDA suppresses EGFRL858R-induced lung adenocarcinoma in transgenic mice suggests that Shp2 PTP is a potential target for therapeutic development in EGFR-driven lung adenocarcinoma." (PMID 25730908, 2015). "The third-generation EGFR inhibitor, afatinib (BIBW-2992), combined super-additively with Debio 1143 to inhibit growth of mutant EGFR lung adenocarcinomas." (PMID 26485762, 2015). "Under these circumstances, our data suggest that the Gab1-Shp2 pathway is activated in these EGFR inhibitor-resistant lung adenocarcinoma cells and promotes tumor growth." (PMID 25730908, 2015). "Our findings also have potential implications for understanding mechanisms of resistance to EGFR-targeted therapies in lung adenocarcinoma." (PMID 26047463, 2015). "A case of relapsed, EGFR exon-19 deletion, lung adenocarcinoma was treated with erlotinib and cisplatin-pemetrexed after resistance." (PMID 25699082, 2015). "We also performed sequencing analysis of MLH1 exon 12 in 51 EGFR-wildtype lung adenocarcinomas and found a comparable incidence (4/51, 7.8%) of the MLH1 V384D allele." (PMID 25823662, 2015). "We recently showed that CIP4 promotes activation of an EGFR/ERK/Zeb1/MMP-2 axis in lung adenocarcinoma cells and tumors, and it will be interesting to further test this axis in CIP4 KD breast tumors." (PMID 25823823, 2015). "Using reporter assays and chromatin immunoprecipitation approaches, it has recently been shown that the EGFR-MEK-ERK1/2 pathway can regulate the transcription of CLDN2 in A549 lung adenocarcinoma cells." (PMID 25823815, 2015). "CRBP-1High expression in lung adenocarcinoma correlated with increased tumor grade and reduced OS, likely through increased Akt/Erk/EGFR-mediated cell proliferation and differentiation." (PMID 26807202, 2015). "In conclusion, this study has identified a novel candidate for genetic predictor of primary EGFR-TKI resistance in EGFR L858R-positive lung adenocarcinomas." (PMID 25823662, 2015). "The superiority of EGFR TKIs (including gefitinib, erlotinib and afatinib) over conventional chemotherapy in advanced lung adenocarcinoma has been well demonstrated in Phase III randomized trials." (PMID 26486077, 2015). "Lung adenocarcinomas have mutually exclusive mutations in receptor tyrosine kinase (RTK) and RAS pathway oncogenes such as EGFR and KRAS." (PMID 26544513, 2015). "A549 cells (human lung adenocarcinoma) were sequentially treated with dye (Cy5)-labelled Erbitux (anti-EGFR monoclonal antibody) and multivalent protein G polygons at 4 °C." (PMID 25972078, 2015). "Six lung adenocarcinoma cell lines, with KRAS, EGFR, or ALK driver mutations were evaluated for Debio 1143 dose-dependent growth inhibition to identify optimal concentrations for use in combination assays." (PMID 26485762, 2015).
lung adenocarcinoma (continued). "In this study, we report our reflex EGFR testing experience on consecutive lung adenocarcinomas seen in an Asian tertiary cancer centre and determine the prevalence of EGFR mutations by gender and smoking status." (PMID 25955322, 2015). "EGFR inhibitors, such as gefitinib and erlotinib, have been developed primarily to target lung adenocarcinoma." (PMID 26160836, 2015). "Patients with EGFR L858R-mutant lung adenocarcinoma have inferior EGFR-TKI treatment outcomes if they have a co-existing MLH1 V384D variant." (PMID 25823662, 2015). "Taken together, our findings offer convincing evidence that the mutual exclusivity of mutant KRAS and EGFR in lung adenocarcinoma is dictated by synthetic lethality." (PMID 26047463, 2015). "Constitutive Gab1-Shp2 binding in human lung adenocarcinoma cells harboring mutant EGFR was observed in a previous study and in this study." (PMID 25730908, 2015). "In EGFR-mutant lung adenocarcinoma cell lines with high BIM expression, concomitant high mTOR expression increased IC50 of gefitinib for cell proliferation." (PMID 26639561, 2015). "Many of these clients are validated oncogenic drivers of lung adenocarcinoma including mutant EGFR, mutant BRAF, wild-type and mutant HER2, and the EML4-ALK translocation product." (PMID 26010604, 2015). "Recent large-scale genomic analyses identified intragenic deletion mutations within the EGFR carboxy-terminal domain in GBM and lung adenocarcinoma." (PMID 25826094, 2015). "A clinical response to EGFR-TKIs in patients with EML4-ALK-positive lung adenocarcinoma has been previously observed in cases that harbour a coexisting EGFR mutation and EML4-ALK translocation." (PMID 25788996, 2015). "Using NSCLC cell lines carrying GOF EGFR mutants and transgenic mice expressing EGFRL858R, we provide evidence that EGFR mutants activate Shp2 in human lung adenocarcinoma cells and in mouse lung tissues." (PMID 25730908, 2015). "The most frequently mutated oncogenes in lung adenocarcinoma are the RAS family GTPases and EGFR (25% and 15% respectively)." (PMID 26413866, 2015). "Knowledge of the molecular profile of advanced lung adenocarcinoma is critical for therapeutic decision-making, particularly in the use of EGFR and ALK tyrosine kinase inhibitors." (PMID 26413866, 2015). "In this study, we show that the EGFR-L858R mutant increases lung adenocarcinoma cell invasion ability and promotes formation of MPE." (PMID 26338423, 2015). "NGS was used to interrogate mutations within hotspot regions of 46 cancer-related genes in lung adenocarcinoma samples from 13 and 16 EGFR-TKI-treated patients who had short (< 3 months) and long (> 1 year) PFS, respectively." (PMID 25823662, 2015). "In our study we used 2 genetically dissimilar human lung adenocarcinoma cell lines: EGFR mutant (exon 21 L858R mutation) T2851 cells and T2821 cells expressing wild type (wt) KRAS and EGFR." (PMID 26517240, 2015). "A total of 190 lung adenocarcinoma patients with classic EGFR exon 19 deletions or L858R experienced disease recurrence." (PMID 26486077, 2015). "Patients with stage IV lung adenocarcinoma with MPE at initial diagnosis have a shorter overall survival and higher rate of EGFR mutations, especially L858R, than patients who develop MPE following disease progression." (PMID 26338423, 2015). "Our results support a potential therapeutic role for a combinatorial epigenetic platform for the treatment of lung adenocarcinoma, particularly in patients with primary EGFR-TKI resistance." (PMID 25925741, 2015). "Given the strong bias in East Asian female populations and correlations with other female-specific cancers, lung adenocarcinoma with EGFR aberrations has very strong links with female patients of papillary and cervical cancers." (PMID 26160836, 2015). "A case report in a letter discussed an 80-year-old male with relapsed EGFR exon-19 deletion lung adenocarcinoma treated with EGFR-TKI." (PMID 25699082, 2015).
lung adenocarcinoma (continued). "A major mechanism of drug resistance to EGFR TKIs in lung adenocarcinoma is reactivation of the mutant EGFR PTK activity." (PMID 25730908, 2015). "From August 2011 to November 2013, a total of 1772 patients with treatment-naïve lung adenocarcinoma were enrolled as Cohort 1 for EGFR, KRAS, BRAF and HER2 genetic analyses." (PMID 25789627, 2015). "In total, these findings suggest that chronic EGFR inhibition in EGFR mutant lung adenocarcinomas can lead to the development of cancers that adopt the genetic, histologic, expression and drug sensitivity profiles of classical SCLC." (PMID 25758528, 2015). "The EGFR exon 20 insertion mutation was also suggested to induce a poor responses to EGFR-TKI, and was reported in about 2% of NSCLC or lung adenocarcinoma, which is similar to our report (2.0%)." (PMID 26599344, 2015). "All of patients in this study had mutant EGFR advanced lung adenocarcinoma and both groups had similar performance status." (PMID 26609535, 2015). "Several clinical studies have shown that a secondary mutation in the tyrosine kinase domain of EGFR (T790M) is responsible for the development of resistance to EGFR-targeting TKIs in approximately half of the cases of lung adenocarcinoma." (PMID 26580964, 2015). "Different classes of genomic alterations involving EGFR identified in cancer, including lung adenocarcinoma and glioblastoma (GBM), have been shown to be responsible for altered EGFR regulation and cellular transformation." (PMID 25826094, 2015). "We examined the in vitro sensitivity of five EGFR-mutant lung adenocarcinoma cell lines to gefitinib." (PMID 26639561, 2015). "To date, the EGFR and KRAS gene mutations, and the EML4-ALK fusion gene have been identified as major oncogenic driver mutations of lung adenocarcinomas." (PMID 26268359, 2015). "Our results revealed that GAS5 is a promising molecule that is capable of overcoming the resistance to EGFR inhibitors in lung adenocarcinoma." (PMID 25925741, 2015). "One of the first and most apparent of these mutually exclusive mutational combinations involves two well-studied proto-oncogenes, KRAS and EGFR, in human lung adenocarcinomas (LUAD)." (PMID 26047463, 2015). "In this study, the mutant EGFR advanced lung adenocarcinoma patients were collected from the cohort database." (PMID 26609535, 2015). "Several acquired resistance mechanisms of EGFR-mutant lung adenocarcinoma to EGFR-TKI therapy were described, the most recent being transformation to SCLC." (PMID 25699082, 2015). "Recent reports have suggested that CPM can be a potential cancer biomarker to discriminate WDLPS from lipomas when coexpressed with EGFR with poor prognosis in adenocarcinoma of lung." (PMID 26643872, 2015). "Patients with EGFR-mutant lung adenocarcinoma develop acquired resistance to EGFR TKIs after a median of 10 to 16 months." (PMID 25699082, 2015). "The driver genes involved in lung adenocarcinoma include KRAS, EGFR, ALK, and BRAF, and those implicated in lung squamous cell carcinoma (LSCC) include PIK3CA, FGFR1, EGFR, PDGFRA, and DDR2." (PMID 26373952, 2015). "Compared with overall gene alterations in Asian lung adenocarcinoma patients, EML4-ALK alterations in our study were relatively increased, and EGFR mutations were relatively reduced." (PMID 26332764, 2015). "‘Exclusivity plots’ for COAD revealed mutations in BRAF to be negatively associated with mutations in KRAS, to a degree similar to that we observed for co-existing mutations of EGFR and KRAS in lung adenocarcinoma." (PMID 26047463, 2015). "MET amplification has been described as one potential mechanism of resistance towards EGFR inhibition in EGFR mutant lung adenocarcinoma." (PMID 26018876, 2015). "Consistently, the Gab1-Shp2 pathway was activated in human lung adenocarcinoma cells containing mutant EGFR." (PMID 25730908, 2015).
lung adenocarcinoma (continued). "We determined that lung adenocarcinoma cells harboring diverse oncogenic mutations such as KRAS and EGFR were sensitized to ionizing radiation." (PMID 26010604, 2015). "In mutant EGFR advanced lung adenocarcinoma patients, the efficiency of TKIs has been demonstrated in other trials." (PMID 26609535, 2015). "It will be important to clarify the relationship of MET and EGFR with ROR1 in lung adenocarcinoma patients." (PMID 25978653, 2015). "A recent report demonstrated that lung adenocarcinoma cases with a co-existence of positive MET FISH status and EGFR mutation had shorter disease-free survival (DFS) as well as OS after resection." (PMID 25886066, 2015). "We identified several targetable pathways in EGFR/KRAS/ALK-negative lung adenocarcinoma including PI3K/mTOR signaling (TSC1, PIK3CA, AKT2), receptor tyrosine kinase signaling (ERBB4), cell cycle regulation (CHEK2, CDC27), and DNA repair (PARP4)." (PMID 24576404, 2014). "We have screened the prevalence of known driver mutations of EGFR, KRAS, HER2, BRAF and ALK in a cohort of 107 lung adenocarcinoma sample with complete prognostic information." (PMID 25198510, 2014). "Common mutations in lung adenocarcinoma include K-RAS, EGFR, as well as translocations of the Anaplastic Lymphoma Kinase (ALK) gene." (PMID 25019058, 2014). "In lung adenocarcinomas, positive and partial positive TTF-1 expression has a significant positive correlation with EGFR mutations(exon 19 and 21)." (PMID 24743427, 2014). "We report a case of leptomeningeal metastasis in epidermal growth factor receptor overexpressing lung adenocarcinoma showing an excellent response with pulsed doses of erlotinib as the only therapy." (PMID 29147411, 2014). "In this study, we demonstrated that hinokitiol inhibited the proliferation and colony formation ability of lung adenocarcinoma cells as well as the EGFR-TKI-resistant lines PC9-IR and H1975." (PMID 25105411, 2014). "EGFR mutations, K-ras mutations and EML4–ALK fusions have been shown to be primarily restricted to lung adenocarcinoma." (PMID 25003505, 2014). "Here, we review advances in targeted treatment of lung adenocarcinoma with respect to five clinically relevant biomarkers – EGFR, ALK, MET, ROS-1, and KRAS." (PMID 25157335, 2014). "Retrospective analysis and subsequent prospective clinical trials have demonstrated that EGFR mutant lung adenocarcinoma benefits from anti-EGFR therapy, although some controversy still exists regarding how best to select these patients." (PMID 25277503, 2014). "Inferred network rewiring of well established Bcl-x and EGFR centered networks from lung adenocarcinoma expression data is in good agreement with literature." (PMID 25034693, 2014). "PC-9 cells and A549 cells, the lung adenocarcinoma cells with mutant and wide-type EGFR respectively, were treated with docetaxel/gefitinib alone or in different combination schedules." (PMID 25474307, 2014). "LUX-Lung 3 was a phase III clinical trial of afatinib compared to cisplatin-pemetrexed chemotherapy in treatment-naïve patients with EGFR-mutant advanced lung adenocarcinoma." (PMID 25157335, 2014). "Here, we reveal the novel mechanisms by which hinokitiol exerts its potent anticancer effects on several lung adenocarcinoma cell lines as well as EGFR-TKI-resistant cells." (PMID 25105411, 2014). "In this study, we demonstrated that hinokitiol significantly inhibited cell proliferation in a series of lung adenocarcinoma cell lines, including EGFR-mutant and TKI-resistant cells, H1975 and PC9-IR, respectively." (PMID 25105411, 2014). "We conducted this study to evaluate the impact of detection methods on the efficacy of erlotinib in patients with advanced EGFR-wt lung adenocarcinoma." (PMID 25215536, 2014). "We analyzed whole exome sequencing data from 16 EGFR/KRAS/ALK-negative lung adenocarcinomas and additional 54 tumors in two expansion cohort sets." (PMID 24576404, 2014).
lung adenocarcinoma (continued). "Relationship between ALK status and clinic, EGFR characteristics in the unselected 368 lung adenocarcinomas." (PMID 24667320, 2014). "Here, we demonstrate that overexpression of RBM5 suppressed EGFR expression, both in lung adenocarcinoma cell line A549 cells and in A549 xenograft tumors." (PMID 25441176, 2014). "In the NEJ 002 clinical study, we found that in patients with lung adenocarcinomas positive for thyroid transcription factor-1(TTF-1) expression, the EGFR mutation rate was higher." (PMID 24743427, 2014). "The discovery of driver mutations, such as epidermal growth factor receptor (EGFR) and anaplastic lymphoma kinase (ALK), has led to remarkable improvements in personalized therapies for lung adenocarcinoma." (PMID 24576404, 2014). "EGFR mutation statuses in matching MPTTs, MPE supernatants and cell blocks, of 41 patients with advanced lung adenocarcinoma as diagnosed by thoracoscopy were analyzed using amplification refractory mutation system (ARMS)." (PMID 24587142, 2014). "Afterwards, we inhibited EGFR expression in the lung adenocarcinoma cell line NCI-H1975 using small interfering RNA, and found that RBM5 expression was not directly regulated by EGFR in non-smoker-related lung adenocarcinomas." (PMID 25441176, 2014). "We recruited the Group-I patients to evaluate the efficacy of erlotinib in patients with EGFR-wt lung adenocarcinoma by either direct sequencing (DS) or mutant type-specific sensitive (MtS) methods in six medical centers in Taiwan." (PMID 25215536, 2014). "In lung adenocarcinomas, STAT3 is one of the most important signaling mediators in both normal and EGFR-mutated tumors." (PMID 25763322, 2014). "A significant portion of the erlotinib responses in EGFR-wt lung adenocarcinoma patients were related to the limitations of detection methods, not only DS but also MtS methods with similar percentages." (PMID 25215536, 2014). "Particularly in lung adenocarcinomas, ERCC1 has been shown to be associated with unchanged EGFR mutation status, to predict response to cisplatin-based therapies and also to be of prognosis value by itself." (PMID 25763322, 2014). "Molecular-targeted therapeutic drugs for activated EGFR have resulted in improvements in response rates and progression-free survival times in lung adenocarcinoma." (PMID 25364428, 2014). "In conclusion, our work illustrated the mutation spectrum of EGFR, KRAS, HER2, BRAF and ALK in lung adenocarcinoma, as well as confirmed that hTERT 5′ promoter region mutation rarely occurred in NSCLC samples." (PMID 25198510, 2014). "Recently, Dogan and colleagues investigated SOX2 and EGFR inhibitors in lung adenocarcinoma cell lines." (PMID 25114775, 2014). "EGFR, KRAS, HER2, BRAF mutation and ALK fusion were mutated in 25.2%, 6.5%, 1.9%, 0.9% and 3.7% of lung adenocarcinomas." (PMID 25198510, 2014). "PC-9 and HCC827 are human lung adenocarcinoma cell lines with deletions of exon 19 in EGFR, resulting in constitutive activation of this protein." (PMID 23690929, 2013). "With the exception of the EGFR-positive tumors, the majority of lung adenocarcinomas with PC have poor prognoses." (PMID 24137394, 2013). "EGFR and KRAS mutations are the two most frequent oncogenic events in human lung adenocarcinoma, occurring in approximately 15% and 30% of U.S. lung adenocarcinoma cases, respectively." (PMID 24255704, 2013). "We also showed that PCV < 2.2 ng/ml was a predictor of a favorable outcome in both advanced lung adenocarcinoma patients with wild-type and mutant EGFR." (PMID 23879483, 2013). "The present study employed the human lung adenocarcinoma cell line PC9, which possesses an EGFR exon 19 deletion mutation that renders EGFR sensitive to the TKIs." (PMID 24100792, 2013). "Functionally, TTF-1 induced ROR-1 is necessary to sustain the EGFR signaling pathway in lung adenocarcinoma cell lines." (PMID 23922984, 2013).